ARHGEF25 (Rho guanine nucleotide exchange factor 25)
Description:
May play a role in actin cytoskeleton reorganization in different tissues since its activation induces formation of actin stress fibers. It works as a guanine nucleotide exchange factor for Rho family of small GTPases. Links specifically G alpha q/11-coupled receptors to RHOA activation. May be an important regulator of processes involved in axon and dendrite formation. In neurons seems to be an exchange factor primarily for RAC1. Involved in skeletal myogenesis (By similarity).
Synonyms: GEFT; p63RhoGEF
Tractability: Small molecule: a structure with a bound ligand is known. Antibody: UniProt places it where antibodies can reach, with medium confidence; its Gene Ontology location is reachable by antibodies, with medium confidence.
Gene: Protein-coding gene on chromosome 12 (57,610,180 to 57,617,245, forward strand). Ensembl gene ENSG00000240771.
Subcellular location: Cell membrane; Cytoplasm, myofibril, sarcomere
Pathways (Reactome):
Signal Transduction: CDC42 GTPase cycle; G alpha (q) signalling events; RAC1 GTPase cycle; RHOA GTPase cycle; RHOB GTPase cycle; RHOC GTPase cycle
Gene Ontology:
Molecular function: guanyl-nucleotide exchange factor activity
Biological process: axon guidance; regulation of small GTPase mediated signal transduction
Cellular component: cytoplasm; cytosol; extrinsic component of membrane; myofibril; plasma membrane; sarcomere
Genetic constraint (gnomAD): Loss-of-function variants: 45 observed, 75.71 expected, observed/expected ratio (o/e) 0.59, 90% interval 0.47 to 0.76. The upper end of that interval is the gene's LOEUF score, 0.76, which puts it in group 3 of 6, group 1 being the genes least tolerant of losing a copy. Missense variants: 621 observed, 729.55 expected, observed/expected ratio (o/e) 0.85, 90% interval 0.8 to 0.91. Synonymous variants: 278 observed, 280.43 expected, observed/expected ratio (o/e) 0.99, 90% interval 0.9 to 1.1.
Homologues: Orthologues: chimpanzee ARHGEF25 (95% identical), macaque ARHGEF25 (93% identical), guinea pig ARHGEF25 (91% identical), pig ARHGEF25 (90% identical), dog ARHGEF25 (89% identical), mouse Arhgef25 (85% identical), rat Arhgef25 (84% identical), zebrafish ARHGEF25 (49% identical). Paralogues in human: TRIO (46% identical), KALRN (43% identical), MCF2L (22% identical), MCF2 (21% identical), PLEKHG4 (20% identical), PLEKHG4B (20% identical), PLEKHG1 (18% identical), MCF2L2 (18% identical), ARHGEF40 (18% identical), PLEKHG2 (17% identical), TIAM1 (15% identical), VAV2 (15% identical), and 10 more.
Diseases named in the same sentence as ARHGEF25 in open-access papers:
ARHGEF25 is named in the same sentence as 9 diseases in open-access papers, as found by Europe PMC text mining. Sharing a sentence is not in itself a finding about the gene and the disease. The quoted sentences say what the papers report.
tumor (11 papers, 2014 to 2025). "ARHGEF25 promotes tumor cell migration, and serum-induced ARHGEF25 activation plays a key role in chemotactic migration by restricting lamellipodia formation to the direction of cell movement and keeping it at the leading edge." (PMID 37538176, 2023). "Another mechanism by which miR-29 exerts tumor suppressive effects in RMS is through targeting guanine nucleotide exchange factor T mRNA (ARHGEF25/GEFT), whose overexpression correlates with poorer outcomes." (PMID 36033507, 2022).
cardiovascular disease (1 paper, 2018). "DNA methylation (such as ARHGEF25, CD2485, and IVRT) was also associated with age and cardiovascular disease." (PMID 30555415, 2018).
ARHGEF25 also shares sentences with these, for which no sentence is quoted: rhabdomyosarcoma (5 papers); breast carcinoma (2); cancer (2); colon cancer (2); colorectal cancer (2); essential hypertensive (1); T-cell lymphoma (1).